ITGB2 (integrin subunit beta 2)
Diseases named in the same sentence as ITGB2 in open-access papers (continued):
Sharing a sentence is not in itself a finding about the gene and the disease.
tumor (170 papers, 2004 to 2026). "The study reveals that ITGB2 facilitates the activation of cancer‐associated fibroblasts (CAFs), enhancing tumor progression and providing potential therapeutic implications for targeting ITGB2 in TNBC treatment." (PMID 40071217, 2025). "ITGB2 enhances TNBC progression by activating cancer‐associated fibroblasts (CAFs) within the tumor microenvironment, promoting tumor growth, migration, and invasion." (PMID 40071217, 2025). "Related studies have shown that ITGB2 mediates mitochondrial glycolytic transformation in cancer-associated fibroblasts and participates in tumor occurrence, metastasis and invasion of cancer cells." (PMID 38345576, 2024). "Tumor infiltration analysis indicates that ITGB2 is associated with immune cells such as dendritic cells, macrophages, monocytes, neutrophils, and B cells." (PMID 39458936, 2024). "Our results show that NCFs and their coexpressed genes, including SPI1, HCK, VAV1, CD53, and ITGB2, are significantly associated with tumor-infiltrating immune cells, especially with immunosuppressive macrophages." (PMID 34708124, 2021). "After the combined treatment, it was found that two EZH2 target genes were upregulated, namely the tumor suppressor gene RASSF5 (ras association domain family member 5) and ITGB2 (integrin subunit Beta 2), which is associated with anti-tumor immunity." (PMID 32751889, 2020). "Our in vitro co-culture studies identify a regulatory loop whereby tumor-associated collagen recognition by CD18 (ITGβ2) on leukocytes upregulates LAIR1 expression, which subsequently promotes CD8+ T cell exhaustion through SHP-1 signaling." (PMID 32908154, 2020). "Likewise, ITGB2 is closely associated with tumor progression, contributing to cancer development, metastasis, and invasion." (PMID 41181127, 2025). "(2018) demonstrated that YAP can substantially enhance the expression of Integrin α L and ITGB2 in tumor cells, facilitated by PR domain zinc finger protein 4 (PRDM4), an important regulatory molecule." (PMID 41601682, 2026). "Mechanistically, we explored the role of tumor EV ITGB2 in activating CAFs both in vitro and in vivo." (PMID 40071217, 2025). "In this study, we detected elevated levels of ITGB2 in tumor tissues, serum EVs from TNBC patients, and human TNBC cell lines." (PMID 40071217, 2025). "For the first time, we proposed that ITGB2 expression in infiltrating macrophages within ESCC increases as these macrophages undergo tumor‐promoting polarization." (PMID 39825491, 2025). "In our study, we found that ITGB2 expression in ESCC‐infiltrating macrophages increases as these macrophages develop towards a tumor‐promoting (M2) phenotype." (PMID 39825491, 2025). "This indicates that the expression of ITGB2 within macrophages increases progressively as they evolve towards a tumor‐promoting phenotype." (PMID 39825491, 2025). "When exosomes enriched with ITGA6 or ITGB2 protein were co-cultured with mouse ovarian cells, we observed that the ovarian cells uptook more tumor-derived ITGA6- or ITGB2-high exosomes compared to those derived from control cells." (PMID 40860157, 2025). "Tumor-derived exosomal factors, particularly integrin beta-2 (ITGB2), suppress TLR4 expression on DCs, leading to impaired DC maturation and reduced cytokine secretion." (PMID 41007774, 2025). "Neutrophil-monocyte interactions involved ICAM1-(ITGAV+ITGB2) pairing, with dysregulation promoting pro-tumor TAM differentiation." (PMID 40948800, 2025). "Consistent with Western blot results, higher ITGB2 IHC staining signals were detected in tumor tissues compared to adjacent normal tissues (4.72 ± 1.49 vs 3.07 ± 2.52, P = 0.020)." (PMID 40071217, 2025). "Based on the total ITGB2 staining score in tumor tissues, patients were divided into ITGB2 low expression (n = 120) and high expression groups (n = 80)." (PMID 40071217, 2025).
tumor (continued). "We present for the first time the finding that the expression of ITGB2 in infiltrating macrophages increases as these macrophages polarize toward a tumor‐promoting phenotype in ESCC." (PMID 39825491, 2025). "Consistent with previous findings, we found that tumor ITGB2 was negatively correlated with overall survival in TNBC patients." (PMID 40071217, 2025). "Since ITGB2 is strongly correlated with immune cells, it is possible to investigate the role of ITGB2 in the tumor microenvironment and immune cell infiltration of OC." (PMID 38814534, 2024). "Findings indicated a notable decrease in both tumor size and mass in the ITGB2 knockdown group, in contrast to the NC group." (PMID 38345576, 2024). "Silencing ITGB2 significantly decreased cell proliferation and suppressed tumour growth, indicating that ITGB2 is a tumour‐promoting gene in CRC." (PMID 39088353, 2024). "The purity of tumor cells decreased upon the increase of ITGB2, indicating increased immune-cell infiltration with elevated expression levels of ITGB2." (PMID 38814534, 2024). "LFA-1/ITGB2 is an important immune cell integrin that is a biomarker of tumor inflammatory infiltrates." (PMID 37435077, 2023). "According to the LGG and GBM cohort of TCGA, the expression of ITGB2 in LGG was negatively correlated with tumor purity (r = 0.369, P < 0.05)." (PMID 36714574, 2022). "We analyzed the correlation between ITGB2 and various tumor-infiltrating cells and found that ITGB2 was positively correlated with MDSC and regulatory T cells." (PMID 36362654, 2022). "We also confirmed that ITGB2 regulates tumor cell proliferation, invasion, and migration through experiments in vitro." (PMID 36362654, 2022). "Meanwhile, we also investigated the expression of ITGB2 at various stages of tumor progression using the UALCAN database." (PMID 36362654, 2022). "Hypoxia-induced activation of the SMAD3 pathway through increased SMAD3 bioavailability and recruitment to the adapter protein SARA induced tumor progression and cancer cell invasion, events associated with the expression of SMAD3 gene targets ITGB2 and VIM." (PMID 35681731, 2022). "In the present study, we found that the expression level of ITGB2 in NSCLC tumor tissues was lower than that in normal tissues, and its low expression was related to an inferior prognosis." (PMID 36362654, 2022). "The biological function analysis showed that the overexpression of ITGB2 can inhibit the proliferation, migration, and invasion ability of tumor cells." (PMID 36362654, 2022). "The expression of ITGB2 in GBM was negatively correlated with tumor purity (r = 0.559, P < 0.05) and CD8+T cells (r = 0.414, P < 0.05)." (PMID 36714574, 2022). "The potential role of ITGB2 in tumor immunology in LGG provides new insight into the immunotherapy of LGG." (PMID 36714574, 2022). "It was reported that ITGB2, which is mainly expressed on the surface of leukocytes, can recruit tumor cells by combining ICAM." (PMID 33816236, 2021). "The immune infiltration analysis of CCR5, FCER1G, and ITGB2 indicated their roles in regulating tumor immunology in EC." (PMID 33995630, 2021). "Results showed that ITGB2 was widely distributed throughout the tumor microenvironment, including cancer cells, TILs and CAFs." (PMID 33204328, 2020). "Clinical data and function-based experiments were used to investigate the promoting tumor growth ability of ITGB2 expressing CAFs." (PMID 33204328, 2020). "On the other hand, gene expression analyses confirmed that proteins related to the complement activation, such as C1QA, SERPING1, A2M, ITGAM and ITGB2, were significantly overexpressed in P3 tumours, compared to P1 and P2 subtypes." (PMID 31560832, 2019). "It has been reported that ITGB2 belongs to integrin family, which was closely related to various tumor growth and metastasis." (PMID 29941860, 2018).
tumor (continued). "The pro-apoptotic CD14, TIA1, and ITGB2 were down-regulated in more than 50% of the tumor cultures after treatment with doxorubicin, as was the antiapoptotic YWHAH." (PMID 18959781, 2008). "This discovery not only uncovers a novel role for YAP in tumor invasion but also clarifies the mechanism by which Integrin α L and ITGB2 contribute to the invasive behavior of tumor cells, specifically by enabling their traversal across the endothelial cell layer." (PMID 41601682, 2026). "Elevated ITGB2 expression subsequently promotes tumor lung metastasis." (PMID 42086529, 2026). "ITGB2 may contribute to the process, but it is important to acknowledge the complexity of the tumor microenvironment, where multiple signals and molecules interact to drive CAF activation." (PMID 40071217, 2025). "These in vivo results suggest that tumor ITGB2 promotes TNBC tumorigenesis." (PMID 40071217, 2025). "This suggests that inhibiting ITGB2 expression might prevent the macrophages from adopting a tumor‐promoting role, although further experimental validation is required to confirm this hypothesis." (PMID 39825491, 2025). "Importantly, we discovered that ICAM1 binding to the ITGAX/ITGB2 heterodimer facilitates neutrophil-monocyte crosstalk, skewing monocyte differentiation toward pro-tumor TAMs and fostering tumorigenesis." (PMID 40948800, 2025). "Although the research primarily focused on CAFs within tumor microenvironments, ITGB2, as an integrin family member, may similarly regulate oxidative stress responses in immune cells, highlighting its potential broader functional significance." (PMID 40369957, 2025). "While this study primarily investigated how ITGB2 in TNBC cells influences CAFs, we speculate that ITGB2 may mediate communication between tumor cells and other TME components through various mechanisms, which warrant further investigation." (PMID 40071217, 2025). "Notably, we found that USP7 inhibition increased gene expression levels of ICAM‐1 (log2 fold changes = .85, padj = .017), VCAM‐1 (log2 fold changes = .72, padj = 1.9 × 10−4), and ITGB‐2 (log2 fold changes = 1.26, padj = 1.84 × 10−4) in the tumour." (PMID 38602256, 2024). "Silencing of ITGB2 decreased cell proliferation and tumour growth in vitro and in vivo, which may provide a new therapeutic approach for IBD or CAC." (PMID 39088353, 2024). "An example involves mutations in the histone methyltransferase EZH2, whose activity causes reduced expression of RAS association domain-containing protein 5 (RASSF5) and integrin beta chain-2 (ITGB2); these are proteins that are involved in anti-tumor response." (PMID 38672652, 2024). "Moreover, the TIMER database showed that ITGB2 was mostly relevant with tumor-infiltrating immune cells with the |Rho (Spearman's coefficient) ∣ more than 0.5." (PMID 38814534, 2024). "On the other hand, TECs also might contribute to lymphocyte migration into the tumor via ICAM1/ICAM2-(ITGAL + ITGB2) interactions with T/NK cells." (PMID 39093451, 2024). "In this study, we firstly revealed that the level of some proteins (such as NRP2, TIMP1, ITGB2, ITGAM) associated with tumor metastasis promotion was decreased in the exosomes derived from MNDA knockdown M2 macrophages, which could be taken up by HCC cells." (PMID 38904028, 2024). "The HE assay showed that ITGB2 silencing decreased the number of tumour cells." (PMID 39088353, 2024). "Additionally, ITGB2 silencing inhibited tumour growth in vivo and decreased tumour volume and weight." (PMID 39088353, 2024). "The silence of ITGB2 suppressed cell proliferation and tumour growth in vitro and in vivo." (PMID 39088353, 2024). "Furthermore, the interaction between UM tumor cells and CD8+ T-cells has been associated with poor prognostics and was stronger in BAP1-mutant cells using the activation of ITGB2 (integrin subunit beta 2) and ICAM1 (intercellular adhesion molecule 1)." (PMID 38920653, 2024).
tumor (continued). "Characterization of tumor immune cell infiltration in BRCA-ness demonstrated an association with suppressive tumor associated TREM2 macrophages expressing marker genes, such as LILRB4 and ITGB2, which were found to be downregulated by combination therapy." (PMID 37872395, 2023). "ITGB2 is vital in various diseases and cancers, especially tumor immunotherapy and migration." (PMID 36714574, 2022). "A motility gene expression study indicated that SMAD3 selectively increased the expression of ITGB2 and VIM, two genes that were found to be implicated in hypoxia-induced cell invasion and associated with tumor progression and metastasis in cohorts of cancer patients." (PMID 35681731, 2022). "Overall, these findings suggested that ITGB2 may be a tumor suppressor in NSCLC malignant phenotypes." (PMID 36362654, 2022). "The increased expression of ICAM1 and ITGB2, which mediate cell adhesion, may lead to enhanced tumor aggressiveness." (PMID 36159780, 2022). "These pieces of evidence suggest that ITGB2 participates in the regulation of tumor immune microenvironment mainly by regulating B cells, CD4+T cells, macrophages, neutrophils, and dendritic cells in LGG and plays an active role in immune infiltration and immune response." (PMID 36714574, 2022). "Transwell and wound healing assays further verified that LINC01272/miR-876/ITGB2 axis could regulate invasion and migration of tumor cells." (PMID 34093798, 2021). "uncovered the higher ITGB2 expression in CAFs promote tumor proliferation in OSCC by activating the PI3K/AKT/mTOR pathways and NADH oxidation in the mitochondrial oxidative phosphorylation system, and ITGB2 was found to be involved in the proliferation, migration, and invasion of CRC cells." (PMID 34926275, 2021). "The role of ITGB2 in the tumorigenesis and the tumor metastasis needs further investigation." (PMID 33995630, 2021). "Besides, ITGA4/AL/AM/AX and ITGB2/B7 obviously correlate with TILs, particularly strongly correlate with monocyte, M2 macrophage and exhaustion T cells, which usually play pro-tumor and immunosuppressive role in cancer." (PMID 32765584, 2020). "Additionally, we found potentially attractive targets in CD96 and CD18 (ITGB2), each of which has demonstrated some significant impact on anti-tumor immunity in pre-clinical studies with the potential for translation in the future." (PMID 32059711, 2020). "Similarly, the colony forming number of HSC3 increased when ITGB2 was overexpressed and decreased when ITGB2 was silenced, indicating ITGB2-expressing CAFs promoted tumor cell proliferation." (PMID 33204328, 2020). "Moreover, TECs also interacted with T/NK cells via ICAM1/ICAM2-(ITGAL + ITGB2), which might contribute to immune cell infiltration and effective anti-tumor immune response." (PMID 39093451, 2024). "In our research, we explored the expression of ITGB2 in tumor and normal tissues, and the results confirmed that a higher expression of ITGB2 was correlated with a better prognosis in patients, suggesting that ITGB2 may be used as a molecular diagnostic marker in LUAD and LUSC." (PMID 36362654, 2022). "Also, TGFB1, ENG, B2M, HLA-F, SELPLG, and ITGB2 were significantly increased in tumor-associated macrophages, compared with those nontumor-associated macrophages." (PMID 36249427, 2022). "Our analysis reveals a dual role of T cell-macrophage crosstalk: CD4+ and CD8+ exhausted T cells drive anti-tumor M1-like TAMs activation via TNF-TNFRSF1A, TNFSF14-LTBR, and ICAM1-ITGAL/ITGB2." (PMID 42001468, 2026). "Beyond its tumor-intrinsic effects, we observed FAHD1+epi cells actively reshaping the TME through ITGB2-dependent crosstalk with CAFs." (PMID 40814172, 2025). "In this study, we explored the role of ITGB2 in TNBC, focusing on its expression in tumor tissues, serum EVs, and its influence on tumor progression and the TME." (PMID 40071217, 2025).
tumor (continued). "Low and high neoplastic are in multiple tumor malignant progression-related pathways such as MIF, ITGB2, and FN1 with different cells for messaging." (PMID 40303412, 2025). "In OSCC, ITGB2+CAFs activate the PI3K/AKT/mTOR axis via NADH oxidation during mitochondrial oxidative phosphorylation, accelerating tumor proliferation." (PMID 41430036, 2025). "To evaluate the effect of tumoral ITGB2 on CAFs within the TME, we measured protein levels of CAF activation markers α‐SMA, FAP, and FSP in tumor tissues using Western blot analysis." (PMID 40071217, 2025). "In this study, we evaluated the expression of ITGB2 in human TNBC tissues, cells, and serum EVs, as well as the relationship between tumor ITGB2 expression and disease progression and prognosis." (PMID 40071217, 2025). "Mechanistic studies demonstrate that EV ITGB2 facilitates CAF activation, driving tumor‐stroma interactions that support TNBC progression." (PMID 40071217, 2025). "Puerkaiti observed that ITGB2 expression was upregulated in TNBC, and its expression level was closely related to tumor stage, local metastasis and clinical prognosis." (PMID 38345576, 2024). "Many signals favoring tumor cells were significantly activated in C2, such as integrin-related signals (COL9A3 − (ITGA2+ITGB1), JAM3 − (ITGAM+ITGB2), COL6A1 − (ITGA1+ITGB1)), immune suppression signals (CD99 − PILRA), etc.." (PMID 39391717, 2024). "Studies have reported that LINC01272 promotes EMT and metastasis by regulating miR‐876/ITGB2 in CRC, indicating that ITGB2 is involved in tumour metastasis in CRC." (PMID 39088353, 2024). "Among stromal fibroblast cells, ITGAV, ITGA1, ITGB1, and ITGB5 were significantly upregulated following IO and, notably, isolated tumor cells found in the stroma showed upregulation of B2M, VIM, ITGA5, ITGB2, and ITGA3." (PMID 39639369, 2024). "Among these genes, FCGR2A, FYN, ITGB2, and VSIG4 protein levels were increased in tumor tissues, while MMP9 protein level was decreased, which was consistent with their mRNA expression levels." (PMID 38022584, 2023). "Subsequently, we attempted to perform immunohistochemistry (IHC) staining for NRGs (CYBB, ITGB2, ITGAM, LILRB2, TLR2, and TLR7) in kidney sections from ANCA-GN patients and age- and sex-matched ccRCC patients with adjacent non-tumor tissues." (PMID 37465687, 2023). "The expression of ITGB2 and ITGAM in the dataset GSE9476 was also higher in tumor samples compared with donors." (PMID 35501867, 2022). "A functional relationship was found between LCP1, ITGB2, and IKZF1, suggesting that these genes regulate tumor immunology in COAD by regulating MDSC infiltration." (PMID 36230637, 2022). "The expression of ITGA4, ITGA8, ITGB2, ITGB7 and ITGB8 was correlated with the infiltration of all types immune cell and tumor purity in the SKCM TIME." (PMID 34660316, 2021). "Among the integrin β‐subunits, ITGB1, ITGB2, ITGB4, ITGB5, ITGB6, ITGB7, and ITGB8 were highly expressed in tumour tissues compared with normal tissues." (PMID 34709754, 2021). "The migration of immune cells to tumor environment is the first step to exert their effects, therefore we selected the genes related to leukocyte migration, including IL-1β, ITGA4, ITGB2, ITGB7, CAV1, and MAG." (PMID 32358484, 2020). "Especially, the candidates ABCA1, MET, and SCD were entangled with tumor metabolism, while FCGR1A and ITGB2 showed the widest interactions with immunological processes." (PMID 32228647, 2020). "IHC analyses of tumor tissues revealed that the expression of Ki67, MCT1 in tumor cells and LDHB in CAFs was enhanced in cancer cells when ITGB2 was overexpressed in CAFs." (PMID 33204328, 2020). "MMP8, ITGB2, and CLDN1 are well-studied proteins that have evolved with tumor cell’s higher ability for invasion." (PMID 29520031, 2018). "Hutterer found that ITGB2 expression in CLL patients could be regulated by DNA methylation, thus promoting tumor cell growth." (PMID 38345576, 2024).